MIF (macrophage migration inhibitory factor)
Diseases named in the same sentence as MIF in open-access papers (continued):
Sharing a sentence is not in itself a finding about the gene and the disease.
tumor (continued). "The interactions where non-tumor cells influenced tumor cells included NAMPT → INSR, MIF → CD74 and CXCR4, GRN → SORT1, and CD99 → CD99." (PMID 39095793, 2024). "GBM cell lines and patient tissue show overexpression of MIF and DDT; levels are correlated with tumor recurrence and poor prognosis." (PMID 38732068, 2024). "Gene abundance comparison between the MIF and CXCL pathways revealed significantly higher MIF expression in tumor cells than CXCL12 expression in CD3+αβT cells." (PMID 38386050, 2024). "The proinflammatory cytokines of IL‐1β, IL‐17, MIF, and TNF‐α were significantly increased in tumor represented complex immunity dysregulation and possible molecular mechanisms due to dysbiosis of the microbiome." (PMID 38041547, 2024). "The differential expression of MIF in various cell subtypes within UVM, as revealed by our scRNA-seq analysis, underscores its significance in the tumor microenvironment." (PMID 39916959, 2024). "The MIF/CXCR4 axis was the most common ligand–receptor interaction between macrophages and tumor cells." (PMID 39464891, 2024). "Given the substantial evidence for MIF and DDT in the progression of a variety of tumors, these are highly tractable targets in oncology with potentially tumor-agnostic applications." (PMID 38732068, 2024). "The MIF/CXCR4 axis is the most common ligand–receptor interaction between macrophages and tumor cells." (PMID 39464891, 2024). "Macrophage migration inhibitory factor (MIF), which is mainly produced by both malignant cells and infiltrating leukocytes, has been reported to play a tumor-promoting role in human cancers." (PMID 39507421, 2024). "Specifically, in the MIF, MK, and SPP1 signaling pathways, high-DRS tumor cells acted as key senders and influencers communicating with immune cells." (PMID 38862242, 2024). "Through co‐culture experiments, we observed that MIF was regulated by the TF HIF‐1α, which can promote tumour progression." (PMID 39113235, 2024). "It is known that MIF and DDT influence the TME to enhance tumorigenesis by modulating environmental signals from a predominantly pro-inflammatory to tumor-permissive phenotype." (PMID 39028303, 2024). "Proinflammatory cytokines, including IL‐8, MIF, and TNF‐α, were significantly upregulated in tumor tissues." (PMID 38041547, 2024). "Murine studies corroborated these results, with dual MIF and DDT inhibition exhibiting the most substantial reduction in tumor size, likely due to greater suppression of involved signaling pathways." (PMID 38732068, 2024). "A covalent tautomerase inhibitor of both DDT and MIF, a 4-iodo-6-phenylpyrimidine (4-IPP), attenuated cell proliferation and colony formation in vitro and tumor growth in vivo." (PMID 38178143, 2024). "The interaction between MIF and CD74 can enhance the stability and biological activity of MIF, influencing tumor development and progression." (PMID 38277205, 2024). "Initially, signals from tumor cells to various macrophages in ACP tumor tissues were expressed by ligands for ANXA1 and MIF in tumor cell subtypes, defined as calcification." (PMID 39483146, 2024). "Immunohistochemical analysis showed that both whole-brain irradiation and MIF silence resulted in downregulation of HIF-1α expression in brain metastasis, which improved intra-tumor hypoxia." (PMID 38685050, 2024). "Cellular communication indicated the high-RMRs- expressing tumor epithelial cells had more interactions with microenvironment cells and the receptor-ligand pairs were more in the MDK and MIF signaling pathways." (PMID 39160604, 2024). "CD74, a non-polymorphic type II transmembrane glycoprotein present on the surface of immune and tumor cells, activates ERK, MAPK, and NF-κB signaling upon interaction with MIF and its coreceptor CD44." (PMID 39028303, 2024). "Based on our findings, we observed that PLOD2 + SAA1 + tumor cells were able to communicate with TME cells and act as strong senders and influencers in signaling pathways such as SPP1, MIF, PTN, and MK." (PMID 38951896, 2024).
tumor (continued). "MIF and DDT also drive tumorigenesis by modulating immune populations within the tumor microenvironment (TME) through cytokine-induced signaling." (PMID 38732068, 2024). "MIF, CD74, and CD44 exhibit interplay and mutual regulation mechanisms in tumor development and progression." (PMID 38277205, 2024). "CPSI-1306, which inhibits the enzymatic region of MIF, reduced cellular proliferation and VEGF expression in vitro and reduced tumor growth and neovascularization in vivo." (PMID 38732068, 2024). "In this study, we reported that radiotherapy ameliorated tumor hypoxia, downregulated HIF-1α expression and MIF secretion in NSCLC, and inhibited the binding of MIF to CD74 in microglia." (PMID 38685050, 2024). "The interaction between MIF and CD74 can trigger various signaling pathways related to tumor cell survival and proliferation, such as PI3K/AKT and NF-κB pathways, playing a downstream role in cell survival and proliferation." (PMID 39474111, 2024). "The MIF/CXCR4 axis has been found to contribute to cell survival, drug resistance, and tumor metastasis in multiple types of tumors." (PMID 39464891, 2024). "C1QC+TAMs mostly receive CSF, CXCL, and MIF signals from CAFs, while SPP1+TAMs can communicate with CAFs through the pro-tumor FN1 or VEGF pathways." (PMID 39323622, 2024). "MIF suppresses PAX5 and DMTF1 tumor-suppressor activity and upregulates TAp63 and VLA-4 integrin, collectively enhancing CLL survival and bone marrow tropism." (PMID 38732068, 2024). "We further explored specific communication pathways and discovered that signaling via PTPRM, MIF, MK, PECAM1, and SPP1 was markedly more active in the tumor group compared to the normal group." (PMID 39165361, 2024). "Our study found that there was significant cellular communication between tumor cells and CD8T cells in HNSCC, and the MIF signaling pathway was significantly enriched." (PMID 38625586, 2024). "Our results revealed the main outgoing signals of FDX1 + tumor/epithelial cells were PDGF, WNT, CD46, MHC-1, MIF, and MK pathways, while the primary incoming signals were IFN-II and other pathways." (PMID 38200479, 2024). "Inhibition of MIF and DDT reduces tumor vascularization and angiogenic markers in various cell and animal models." (PMID 38732068, 2024). "Hepatocyte-specific MIF-KO and global CD74 KO mice exhibited reduced tumor burden compared to their WT counterparts." (PMID 38732068, 2024). "This multifaceted role emphasizes the complex interplay of MIF with T cells in KIRC, impacting diverse biological processes such as T‐cell immunomodulation, inflammation and tumour development." (PMID 39031800, 2024). "Over the next few years, Gaberet al. investigated the interaction between the roles of macrophage migration inhibitors (MIF), HIF, and GCs in human primary non-tumor CD4 + Th cells and Jurkat T cells." (PMID 38671500, 2024). "Importantly, our study demonstrated that MIF secretion by TAMs could enhance tumour progression." (PMID 39113235, 2024). "Increased expression of CD44, CXCR4 and CD74 on group 1 and 2 NK cells, on which numerous signals from fibroblasts, endothelial cells, tumor cells and macrophages converged (COLLAGEN, MIF, LAMININ), facilitated the augmented incoming signaling in NSCLC." (PMID 38956379, 2024). "Differential signaling pathways, such as CXCL and MIF-related pathways, were observed between FABP6+ tumor cells and normal tissues." (PMID 38277205, 2024). "In this regard, elevated levels of MYC in tumor cells have been shown to promote PDAC metastasis through CXCL13- and macrophage migration inhibitory factor (MIF)-mediated recruitment of TAMs in a recent study." (PMID 37771596, 2023). "Such as macrophage migration inhibitor (MIF), polytrophic factor (PTN) and cell adhesion related genes (cadherin, cadherin-1 and desmosomes) are highly expressed in the signaling pattern of tumor cells." (PMID 37213285, 2023).
tumor (continued). "In the analysis of L/R pairs, the L/R pairs of MIF/(CD74 + CD44 or + CXCR4) and APP/CD74 were the most prominent interactions involving signal transduction from tumor cells to PCs." (PMID 37138324, 2023). "Up to now, the effects of MIF/DDT small-molecule inhibitors have mainly been tested in vitro and in several murine preclinical tumor and inflammatory models." (PMID 36672343, 2023). "In summary, tumor cell-derived chemokines and cytokines, such as CXCL1/CXCL8 and SRF, recruit MDSCs, TAMs, Treg and Tex, and interact with target genes, like MIF and IFNG." (PMID 37940972, 2023). "Here, we provide an overview of the involvement of both MIF and DDT in cancer, and we propose that blocking both cytokines is needed to obtain the maximum anti-tumor response." (PMID 36672343, 2023). "Nevertheless, we suspect that, in addition to MIF, various other secreted proteins in MYO1B-controled secretome likely work in concert to promote NB tumor progression." (PMID 37611092, 2023). "For example, miR-144/miR-451a, a tumor suppressor in HCC cells, can target HGF and MIF in HCC cells and induce M1 polarization and anti-tumor activity of TAMs via paracrine pathway." (PMID 37274242, 2023). "MIF-(CD74+CXCR4) and MIF-(CD74+CC44) interactions happened in dendritic cells, M1 macrophage, M2 macrophage, monocyte, and plasma cells both in tumor and normal tissues." (PMID 37335089, 2023). "Surprisingly, we found a higher proportion of macrophage C4 in brain metastatic tissues, and this macrophage subpopulation was highly expressed in genes that promote tumor invasion and metastasis, such as CSTB, MMP9, CCL5, and MIF." (PMID 37715019, 2023). "Another cell type known to acquire a pro-tumorigenic phenotype within the TME is the neutrophil; MIF, through the binding of CXCR2, promotes their tumor infiltration." (PMID 36672343, 2023). "The effectiveness of using a combinational therapy including SeNPs, MSCs, and LDR was elucidated by measuring the expression of some genes including Serpin, MIF, LOX-1, COL1A1, FST, and ADRP that play a role in the tumor microenvironment." (PMID 35138531, 2023). "The results showed that CAFs, tumor cells, and B cells can participate in a series of functional interactions involving CXCL12 receptor-mediated APP, COPA, and MIF signaling." (PMID 37719863, 2023). "Glioma cells, stimulated by CD74, also secrete MIF and inhibit their IFN-γ secretion by phosphorylating the ERK1/2 pathway in microglia, inhibiting the shift of microglia to an anti-tumor phenotype." (PMID 37700840, 2023). "In contrast, we found that inflammatory interactions between tumor cells or Scissor+ tumor cells and myeloid cells were significant increased, such as APP‐CD74, and MIF‐(CD74 + CD44)." (PMID 37021816, 2023). "Increased MIF, CNN2, and ARF1 are enriched in IL-12-related pathways, which promote tumor development." (PMID 38072118, 2023). "The most prominent differences concentrated on MIF, CXCL, and interleukin pathways, and tumor cells in the high UVRAG expression group tended to exert a stronger immunosuppressive effect by inhibiting immune cells and recruiting immunosuppressive cells." (PMID 37173968, 2023). "Our results confirmed the spatial proximity of multiple sets of ligands and receptors, such as ANXA1‐FPR1, APP‐CD74, MIF‐(CD74 + CD44), and CD99‐CD99, and they basically correspond to the location of tumor cells, myeloid cells, and T cells, respectively." (PMID 37021816, 2023). "Macrophage migration inhibitory factor (MIF) prevents abnormal trophoblast apoptosis and increases tumor aggression." (PMID 36834865, 2023). "CD36+CAF-derived MIF potentiated the capacity of MDSCs to promote immunosuppressive TME and tumor stemness via IL-6/STAT3 activation." (PMID 38065972, 2023). "Ascites fluid from OC patients contains cancer cells that emit macrophage migration inhibitory factor (MIF), a chemokine that promotes the growth, migration, and metastasis of tumor cells." (PMID 37298230, 2023).
tumor (continued). "Protein Atlas verified that APOE, MIF, and NR3C1 were expressed in tumor tissues at different levels." (PMID 36452480, 2022). "Immunohistochemical analysis of the tumour tissues showed changes in the protein expression of MMP9, vimentin, Bax, Bcl‐2, p‐p65, CDK9, MMP2, N‐cadherin and MIF." (PMID 35060345, 2022). "A previous study indicated that macrophage migration inhibitory factor (MIF) and CXCL7 as tumor proinflammatory factors were identified by proteomics to correlate with clinical stage and development in WT patients." (PMID 35578692, 2022). "Similar to the effect on MDSCs, TA-MSCs, TA-MSCs-EVs and MIF promote the production and recruitment of Tregs in immunosuppressive TME and enhance the expression of immunomodulatory factors, thus enhancing the tumor-promoting effect of Tregs." (PMID 35842634, 2022). "In particular, we discovered that macrophage migration inhibitory factor (MIF), which interacts with CD74+CXCR4+ and CD74+CD44+, was specifically expressed in tumor samples." (PMID 35967424, 2022). "A recent report showed that MIF was overexpressed in TNBC; CPSI-1306 as a MIF inhibitor was found to decrease TNBC tumor growth and metastasis both in vitro and in vivo." (PMID 35414025, 2022). "Glioma cells can secrete IL-8, MIF, and CXCL8, which induce neutrophil infiltration into the tumor site." (PMID 35920986, 2022). "At the same time, GRO-α (CXCL1), MIF and SDF-1α (CXCL12) are able to stimulate tumor growth and progression." (PMID 36613737, 2022). "Here, we explored the MIF/CXCR4 pathway in primary NB tumor biopsies and BM-derived disseminated NB tumor cells (DTCs) using publicly available gene expression datasets." (PMID 35715791, 2022). "The qPCR results revealed that the mRNA levels of RRM2, MIF, PANX1, and EGLN1 were significantly higher in tumor samples than in paired normal samples." (PMID 35311093, 2022). "Several therapeutic strategies under development use antibodies to block MIF or CD74 and thus prevent MIF signaling in different tumor types." (PMID 36352420, 2022). "EGLN1, MIF, PANX1, and RRM2 showed a consistently high expression in 15 tumor samples compared to paired normal tissues." (PMID 35311093, 2022). "Tumor associated macrophage (TAMs) are classically known to promote tumor growth and metastasis, but following treatment with IL-12, TAMs exhibit reduced production of tumor promoting factors (IL-10, MCP-1, MIF, and TGFβ)." (PMID 35634303, 2022). "Macrophage migration inhibitory factor (MIF) is a mediator of MDSC migration and proliferation in the promotion of tumor growth and metastasis." (PMID 35740673, 2022). "The other was to directly connect with tumor cells through the MIF and TNF pathway to play a tumor-promoting role." (PMID 36479092, 2022). "In terms of mechanism, TA-MSCs, TA-MSCs-EVs and MIF reduce the expression of PD-1 in immunosuppressive TME and PD-L1 in tumor cell and immunosuppressive cell, thereby inhibiting anti-tumor immunity and promoting tumor cell immune escape." (PMID 35842634, 2022). "As is well-known, macrophage migration inhibitory factor (MIF) is involved in many carcinogenic processes, including cell proliferation, angiogenesis and inhibition of host tumor cell immune surveillance." (PMID 36686485, 2022). "Th17 cells are generated by tumor-derived IL1β and IL13, and accumulate in tumor tissues in response to various chemokines, including CCL2, CCL5, CCL20, CCL17, CCL22, and MIF, which are produced from tumor cells." (PMID 36211375, 2022). "In NSCLC, ionizing radiation (IR) induces dissociation of the MIF-ribosomal protein S3 (rpS3) complex and enhances MIF expression, which activates the NF-kB signal and triggers EMT of tumor cells." (PMID 35842634, 2022).
tumor (continued). "Another MIF inhibitor, ISO-1, was shown to inhibit pancreatic cancer cell invasion, migration and proliferation in vitro, as well as tumor growth in vivo in an immunodeficient murine model." (PMID 35740692, 2022). "For example, MIF is reported to activate MAPK and its downstream signals via binding to CXCR4 on MSCs, inducing tumor homing of MSCs." (PMID 35842634, 2022). "Knockdown of both MIF and SLC3A2 inhibited tumour growth and metastasis via the AKT/GSK‐3β pathway in vivo." (PMID 35567291, 2022). "For instance, MIF signal is the strongest signal for CSCs to communicate with other cells in TME, and C8 displayed characteristics of immune cells and cancer cells in tumor by expressing different receptors." (PMID 36451812, 2022). "Macrophage migration inhibitory factor (MIF) is a multipotent cytokine involved in both inflammatory processes and anti-tumor immune response, having the properties of an enzyme, chemokine, and hormone simultaneously." (PMID 36046240, 2022). "Particular attention was paid to three of them: Histone H2A type 1-B/E (H2A1B), macrophage migration inhibitory factor (MIF) and Tropomyosin alpha-1 chain (TPM1), which are present only in the tumor zones of R-GBM, in particular in CORE." (PMID 35216175, 2022). "MIF has additionally been shown to inhibit the activation of CD4+, CD8+ T cells and CTLs in the tumor regions of cancer-bearing mice." (PMID 35842634, 2022). "In contrast, MIF(−/−) BALB/c mice have a significantly diminished acute inflammatory response to UVB exposure and reduced tumor incidence with significantly less angiogenesis and delayed tumor progression compared to wild-type mice." (PMID 36146458, 2022). "Further experiments showed that knockdown of MIF and SLC3A2 inhibited tumour growth and metastasis by promoting iron death and regulating the AKT/GSK‐3β pathway in vivo." (PMID 35567291, 2022). "Our findings identify miR-144/miR-451a cluster as a tumor suppressor in HCC, which induce M1-like repolarization of TAMs though paracrine pathway via targeting HGF and MIF." (PMID 33658044, 2021). "In addition, factors related to the tumor microenvironment and secretion of chemokines and MIF (macrophage migration inhibitory factor), a pro-inflammatory cytokine that inhibits the random movement of macrophages, could also be associated with this difference." (PMID 33946188, 2021). "Studies showing that human tumor cells themselves are able to activate MAPK-mediated IL8 and VEGF expression by binding of MIF to its main receptor CD747,12,27,28,35,53 were confirmed within this study in human CRC cells." (PMID 33542244, 2021). "Growth factors and cytokines, such as TGF-β, MIF, IL-6, and SDF-1, which are produced in the TME and are important in the recruitment of MSCs to TME, further augment tumor growth and metastasis by promoting the neovascularization of the tumor." (PMID 34681692, 2021). "TANs are typically found in the center of the tumor bulk and are attracted to the TME via macrophage migration inhibitory factor (MIF), C–X–C motif chemokine ligand 8 (CXCL8), and interleukin 8 (IL-8)." (PMID 34571905, 2021). "Functionally, DDT and MIF overlap significantly in terms of cell survival control, tumor formation, and tumor migration, while DDT and MIF additively regulate the growth and survival of cancer cells." (PMID 34516577, 2021). "Downregulation of MIF in the RMS cell line leads to large xenografts, high stromal cell support, and high tumour cell count." (PMID 34838000, 2021). "We also proved that rSmeg-hMIF-hIL-7 can exert strong anticancer immune responses in various tumor-bearing mouse models (MC38, PanO2 and LLC), which was mediated mainly by eliciting anti-MIF immune responses." (PMID 34389619, 2021). "To further support MIF as tumor-relevant Hsp90 client in CRC progression, we used genetically deleted MIF tumor organoid cultures." (PMID 33542244, 2021).